HGF (hepatocyte growth factor)
Diseases named in the same sentence as HGF in open-access papers (continued):
Sharing a sentence is not in itself a finding about the gene and the disease.
neurofibromatosis type 1 (1 paper, 2018). A clinically heterogeneous, neurocutaneous genetic disorder characterized by cafe-au-lait spots, iris Lisch nodules, axillary and inguinal freckling, and multiple neurofibromas. "Dermal factors have also been identified to be abnormally expressed in pigmentary lesions, such as KGF/FGF7, HGF and SCF in lentigo senilis and an increased secretion of SCF and HGF by dermal fibroblasts in neurofibromatosis type 1 (NF-1) disease." (PMID 30205563, 2018).
neurogenic muscular atrophy (1 paper, 2024). "Among them, hepatocyte growth factor (HGF) can promote peripheral nerve regeneration by activating repair SCs and may also play an important role in neurogenic muscular atrophy." (PMID 39768225, 2024).
nosocomial infection (1 paper, 2015). An infection acquired in a hospital or other healthcare setting. "Statistical dependence between the HGF variables (c-Met, HSPG, and ELISA) and white blood cells was tested in cases having nosocomial meningitis (G3) and other nosocomial infections (G4) by using Spearman’s rho." (PMID 26408034, 2015).
obstructive uropathy (1 paper, 2024). "Another study, using a mouse model, found that hepatocyte growth factor (HGF) attenuates apoptosis in renal cells and reduces the progression of interstitial fibrosis caused by obstructive uropathy." (PMID 39240898, 2024).
ovarian adenocarcinoma (1 paper, 2015). An adenocarcinoma that arises from the ovary. "Additional exogenous HGF stimulation resulted in c-Met phosphorylation and enhanced downstream signaling by elevated p44/42-MAP kinase activation in SCCOHT-1 and the ovarian adenocarcinoma cells." (PMID 26436697, 2015).
ovarian cystadenoma (1 paper, 2012). A benign ovarian surface epithelial-stromal tumor characterized by the presence of cystic structures lined by serous epithelial cells, mucinous columnar epithelial cells, or endometrial-type well-differentiated cells. "We compared the same previous phase 2 HGF concentrations by stratifying them by the nature of oncological disease in the 17 patients, 10 malignant (ECOC) and 7 benign (uterine fibroma, ovarian cystadenoma)." (PMID 22999213, 2012).
ovarian failure (1 paper, 2023). "Therefore, HGF secreted by PD-MSCs improved ovarian function in rats with ovarian dysfunction by decreasing vascular permeability via Wnt signaling." (PMID 38067136, 2023). "In conclusion, our findings indicate that increased HGF induced by PD-MSCs improved ovarian function via dual effects, namely by regulating vascular permeability and inhibiting inflammation, via activated Wnt signaling in rats with ovarian failure." (PMID 38067136, 2023).
overnutrition (1 paper, 2023). An imbalanced nutritional status resulting from excessive intake of nutrients. "Therefore, elevated ChREBP/HGFAC/HGF may promote healthy expansion of adipose tissue for efficient storage of fuel during overnutrition." (PMID 36413406, 2023).
palsy (1 paper, 2018). A general term most often used to describe severe or complete loss of muscle strength due to motor system disease from the level of the cerebral cortex to the muscle fiber. "The rats in the DPSC and DPSC/HGF groups showed significant preservation of posture (DPSCs, p < 0.05; DPSCs/HGF, p < 0.01) and palsy score (DPSCs, p < 0.05; DPSCs/HGF, p < 0.01) compared to those in the vehicle group." (PMID 30151417, 2018).
panic disorder (1 paper, 2014). An anxiety disorder characterized by multiple unexpected panic attacks with persistent concern of recurring attacks. "Additionally, correlations were reported between lower serum HGF levels and fatigue in healthy control participants, as well as between increased serum HGF levels and antidepressant efficacy in patients with panic disorder." (PMID 25047123, 2014).
papilloma (1 paper, 2019). A benign epithelial neoplasm that projects above the surrounding epithelial surface and consists of villous or arborescent outgrowths of fibrovascular stroma. "We measured HGF and p-MET expression in papillomas and SCCs from WT and Tpl2−/− mice." (PMID 30631034, 2019).
peripheral nerve injury (1 paper, 2022). Injury to a peripheral nerve. "VEGF165 and HGF both have been shown to have a neurotrophic modality via corresponding signaling axes and this has become the basis for their application in peripheral nerve injury, central nerve system diseases and neuropathic conditions." (PMID 36497083, 2022).
peritoneal cancers (1 paper, 2020). A peritoneum cancer that is located in the inside of the abdomen. "The HGF/c-MET pathway has been targeted in clinical studies in gastro-oesophageal, ovarian and primary peritoneal cancers, with largely negative results." (PMID 32203220, 2020).
pheochromocytoma (1 paper, 2022). "By interfering with COX4I2 mRNA in fibroblasts, we observed a decrease in the expression of ANG1 and HGF, which suggests that COX4I2 may act as an upstream gene of ANG1 and HGF to mediate a pathway of pheochromocytoma angiogenesis." (PMID 36172142, 2022). "In conclusion, fibroblasts mediate the angiogenesis of pheochromocytoma by increasing COX4I2 expression, possibly by affecting ANG1 and HGF." (PMID 36172142, 2022). "Fibroblasts mediate the angiogenesis of pheochromocytoma by increasing COX4I2 expression, possibly by affecting ANG1 and HGF." (PMID 36172142, 2022).
pneumoconiosis (1 paper, 2024). An occupational lung disorder caused by inhalation of dust particles. "It is worth noting that HGF's anti-inflammatory and anti-fibrotic attributes make it possible to treat pneumoconiosis and alleviate its progression." (PMID 39866352, 2024). "The combination of HGF with nanotechnology or MSCs will be of much significance to the treatment of pneumoconiosis." (PMID 39866352, 2024). "The combination of MSC and HGF has been reported to have good therapeutic effect on some pneumoconiosis patients." (PMID 39866352, 2024). "HGF inhibits fibrotic remodeling, which is mediated by multiple direct and indirect mechanisms, including the induction of cell survival, proliferation of pulmonary epithelial and endothelial cells, and reduction of myofibroblast accumulation, suggesting that HGF can be used to treat pneumoconiosis." (PMID 39866352, 2024).
POEMS syndrome (1 paper, 2021). POEMS syndrome is a paraneoplastic syndrome characterized by polyradiculoneuropathy (P), organomegaly (O), endocrinopathy (E), clonal plasma cell disorder (M), and skin changes (S). "Besides VEGF, other pro-angiogenic and pro-inflammatory factors, such as basic fibroblast growth factor, hepatocyte growth factor, tumor necrosis factor-α, IL-6, and IL-12, are elevated in POEMS syndrome." (PMID 34025681, 2021).
postpartum depression (1 paper, 2023). A type of clinical depression that occurs after childbirth. "Moreover, previous studies found that HGF was elevated in women with postpartum depression, and our present research also found HGF was up-regulated in MDD patients." (PMID 37599893, 2023).
prostate adenocarcinoma (1 paper, 2017). "Seven patients with Stage IV prostate adenocarcinoma, candidates for targeted therapy inhibiting the hepatocyte growth factor/tyrosine-protein kinase Met (HGF/C-MET) pathway, were included in this study." (PMID 28375169, 2017).
psychosis (1 paper, 2022). "Based on our literature review, the HGF clearly outweighs other model types by the number of applications in psychosis studies." (PMID 35492702, 2022). "While learning parameters were not altered in the CPD studies (also due to a different modeling approach, see next section), HGF parameters were found to differ in psychosis." (PMID 35492702, 2022). "In the context of psychosis, the HGF was applied to behavioral responses of the following paradigm types: reversal learning, social advice taking, an implicit salience paradigm, and a modified version of the beads task." (PMID 35492702, 2022).
rectal cancer (1 paper, 2013). A primary or metastatic malignant neoplasm that affects the rectum. "In this regard, the inhibition of the HGF/cMET pathway may, therefore, represent a valid therapeutic approach for rectal cancer patients treated with preoperative chemoradiation, as it could potentially improve outcome by decreasing radiation-induced HGF up-regulation and metastatic potential." (PMID 24005867, 2013).
relapsing-remitting multiple sclerosis (1 paper, 2012). The most common clinical variant of multiple sclerosis, characterized by recurrent acute exacerbations of neurologic dysfunction followed by partial or complete recovery. "Our findings suggest that interferon-β may mediate some of its therapeutic effects in relapsing-remitting multiple sclerosis through the induction of hepatocyte growth factor by blood monocytes by coupling immune regulation and neuroprotection." (PMID 23166786, 2012).
Renal atrophy (1 paper, 2018). Atrophy of the kidney. "Previous studies showed that PPARγ activation by telmisartan exhibited renal protective action in mice with renal atrophy and fibrosis and this prevention by telmisartan is associated with a significantly increased renal HGF expression but attenuated by GW966237." (PMID 30089804, 2018).
salivary gland tumors (1 paper, 2021). "On the other hand, to better understand the effect of this protein on the pathogenesis and invasion of salivary gland tumors, it is suggested that angiogenesis and other markers such as HGF and c-MET be investigated simultaneously with CD138." (PMID 31540870, 2021).
schwannoma (1 paper, 2013). A benign, usually encapsulated slow growing tumor composed of Schwann cells. "In schwannomas, MET and its ligand HGF were expressed in all analyzed samples, as determined by qRT-PCR and immunohistochemistry, although no healthy tissue was used as the control; therefore, no alterations of expression were established." (PMID 23354516, 2013).
scoliosis (1 paper, 2024). A congenital or acquired spinal deformity characterized by lateral curvature of the spine. "In addition, scoliosis was causally related to 4 common IFs, including T-cell surface glycoprotein CD6 isoform, hepatocyte growth factor, interleukin-18, and tumor necrosis factor ligand superfamily members." (PMID 38875409, 2024).
Senile plaques (1 paper, 2021). Senile plaques are extracellular deposits of amyloid in the gray matter of the brain. "This increase in HGF immunoreactivity is most likely due to the proliferation of both reactive microglia and astrocytes around the periphery of senile plaques." (PMID 34615471, 2021).
sensorineural hearing loss (1 paper, 2023). "DFNB39, an autosomal recessive form of non-syndromic sensorineural hearing loss, is caused by mutations in the hepatocyte growth factor gene (HGF)." (PMID 36936679, 2023).
serous ovarian cancer (1 paper, 2015). "In fact in our previous analysis of high-grade serous ovarian cancer patients, both FZD1 and HGF exhibited significant prognostic properties." (PMID 26100469, 2015).
skin melanomas (1 paper, 2013). "Three cell lines were successfully developed from separate back skin melanomas of the HGF+ strain (designated A-T1, A-T2 and A-T3) and HGF+ × [m1m2]+/− hybrid (B-T2, B-T5 and B-T6)." (PMID 22699362, 2013). "The lack of a clear difference in overall invasive index between back skin melanomas of the two mouse groups, indicates that the high metastatic potential associated with the HGF+ × [m1m2]+/− genotype is not determined by overall tumor expansion outside the dermal margins." (PMID 22699362, 2013).
spinocerebellar ataxia type 7 (1 paper, 2020). "On the other hand, HGF is known to be a potential neurotrophic factor, and has been shown to diminish Purkinje cell degeneration in spinocerebellar ataxia type 7 when overexpressed." (PMID 32933002, 2020).
synovitis (1 paper, 2020). Inflammation of a synovial membrane. "We found that without HGF modification, DPSC transfusion was helpful in controlling autoimmune status, local synovitis, and bone erosion after intravenous administration." (PMID 32522231, 2020).
T-cell acute lymphoblastic leukemia (1 paper, 2022). Acute lymphoblastic leukemia of T-cell origin. "The HGF/c-MET signaling pathway is involved in the occurrence and progression of hematological tumors including T-cell acute lymphoblastic leukemias." (PMID 36407095, 2022).
tongue cancer (1 paper, 2021). A malignant neoplasm affecting the tongue. "In this study, we aimed to explore the role of HGF/c-Met signaling in the malignant stage of the oral mucosal epithelium by establishing tongue cancer models of HGF transgenic mice (HGF-Tg) and wild-type (Wt) mice induced by chemical carcinogens (4NQO)." (PMID 34970484, 2021).
tonsillar carcinomas (1 paper, 2015). "Particularly HPV negative tonsillar carcinomas with HGF or MET over-expression where associated with a reduced survival." (PMID 25633809, 2015).
trigeminal neuralgia (1 paper, 2021). Trigeminal neuralgia is a nerve disorder that causes a stabbing or electric-shock-like pain in parts of the face. "In the present study patients with trigeminal neuralgia showed lower levels of growth factor levels such as Ang-2, bFGF, HGF, SCF, TGF-α, and VEGF and higher cytokine levels of IL-1β, TNF-α, CCL2, IL-17A, IL-6, and CXCL8 in comparison with normal individuals." (PMID 34067581, 2021).
type 1 diabetes (1 paper, 2020). "The mechanism is potentially related to reduction in inflammatory responses as plasma levels of TNF-α and GRO-α were decreased, while the cell survival marker HGF was increased in human islets exposed to a type 1 diabetes-like milieu in vitro and in vivo." (PMID 32350565, 2020). "Furthermore, we demonstrated upregulation of HGF in islet grafts in the early phase post transplantation and in human islets exposed to a type 1 diabetes-like milieu and treated with GPR44 antagonist in vitro." (PMID 32350565, 2020).
urothelial bladder cancer (1 paper, 2021). "According to the Pathology Atlas of the Human Cancer Transcriptome high mRNA expression of HGF or CDK4 in urothelial bladder cancer correlates with a worse overall survival compared to patients with low expression of these genes (P-scores: HGF 0.021 and CDK4 0.016)." (PMID 34232958, 2021).
Urothelial Carcinoma of (1 paper, 2014). "There is mounting evidence of oncogenic hepatocyte growth factor (HGF)/Met signaling in urothelial carcinoma (UC) of the bladder." (PMID 25534569, 2014). "A prior study of 5 rat urothelial carcinoma-derived cell lines also found that all expressed Met, whereas only one appeared to express HGF; oddly, the latter cell line was refractory to endogenously added HGF in cell growth and invasion assays." (PMID 25534569, 2014).
venous thromboembolism (1 paper, 2014). Occlusion of the lumen of a vein by a thrombus that has migrated from a distal site via the blood stream. "Interestingly, an increased incidence of venous thromboembolism has also been observed in the setting of HGF/MET inhibition possibly supporting the notion that anti-HGF/MET drugs can disrupt the functioning of the vascular endothelium." (PMID 24930887, 2014).
vitiligo (1 paper, 2021). Generalized well circumscribed patches of leukoderma that are generally distributed over symmetric body locations and is due to autoimmune destruction of melanocytes. "For example, an increased synthesis and production of IL-1β, IL-6 and hepatocyte growth factor (HGF) genes were found in vitiligo fibroblasts when compared against normal control cells." (PMID 34960102, 2021).
Werner syndrome (1 paper, 2020). "Through correction of the Werner syndrome (WS) causative gene WRN, the paper reports a mechanism of HGF insufficiency in WS MSC and its connection with the impaired pro‐angiogenesis function." (PMID 32320127, 2020).
Zinc deficiency (1 paper, 2019). A deficiency of the essential metal Zinc; an essential cofactor for many enzymes. "Other experimental studies indicate that zinc deficiency decreased cell proliferation and related proteins such as hepatocyte growth factor (HGF), insulin like growth factor I (IGF), IGF binding protein 1 (IGFBP-1), MT, and cyclin D1, along with HNF-4α protein." (PMID 31174269, 2019).
tumor (2,103 papers, 1993 to 2026). "We have previously demonstrated that in NSCLC tumors harboring MET exon 14 mutations, HGF is expressed in about half of the tumor cells." (PMID 39980226, 2025). "The tumor microenvironment also plays a pivotal role; stromal fibroblasts and tumor-associated macrophages can secrete hepatocyte growth factor, activating c-MET signaling and reinforcing resistance phenotypes." (PMID 41302945, 2025). "Tumor-associated stromal cells (CAFs) secrete growth factors such as the hepatocyte growth factor (HGF), which activates the MET pathway." (PMID 40002260, 2025). "We demonstrated that VS-induced SNHL was linked to increased secretion of TNF-α, IL-2R, CD163, eotaxin, and HGF, while larger tumor size was associated with higher levels of TNF-α, TNF-R2, IL-1α, IFN-α, MIP-1β, and IL-21 secretion." (PMID 39923035, 2025). "Elevated IdoA content in tumor-associated DS enhances hepatocyte growth factor (HGF)-mediated signaling and ERK1/2 activation, a pathway that YKL-40 is also known to modulate." (PMID 41149582, 2025). "For example, hepatocyte growth factor (HGF) produced by tumor-associated fibroblasts (CAFs) and macrophages (TAMs) activates survival pathways, reinforcing temporary drug-tolerance." (PMID 40894234, 2025). "Stromal-tumor interaction analyses revealed that cancer-associated fibroblasts (CAFs), particularly matrix CAFs (mCAFs), promote malignant progression via the HGF-MET-MYC signaling axis." (PMID 41234356, 2025). "The tumor microenvironment produces key regulators of cancer growth and metastasis, including growth factors such as hepatocyte growth factor (HGF), a growth factor that is produced by cancer-associated fibroblasts." (PMID 40723207, 2025). "Abnormal activation of the hepatocyte growth factor (HGF) and c-mesenchymal–epithelial transition factor (c-Met) signaling pathway is associated with tumor occurrence and development." (PMID 40823073, 2025). "It has been shown in colorectal cancer that HGF expressed by associated fibroblasts stimulated tumour adhesion through up-regulation of CD44 via c-Met signalling pathway." (PMID 38783165, 2024). "Activation of wild-type MET contributes to drug resistance, not only due to receptor overexpression but also as a result of paracrine HGF secretion by tumor-associated stromal cells." (PMID 39598385, 2024). "HGF plays a role in the progression of HCC by promoting the proliferation of tumor-associated fibroblasts (CAFs) in diabetic MASH33." (PMID 39394459, 2024). "Dysregulation of HGF/c-MET signaling in NSCLC is associated with tumor proliferation, angiogenesis, invasion, metastasis, and acquired drug resistance." (PMID 39201787, 2024). "In head and neck cancer (HNC), HGF primarily functions as a paracrine factor, secreted by cancer-associated fibroblasts, making it prevalent in the tumor micro-environment." (PMID 39769452, 2024). "Cancer-associated fibroblasts signal to the cancer cells for tumour growth and angiogenesis via pathways such as HGF, ANGPTL4, HBEGF and FGF." (PMID 39149248, 2024). "MET pathway activation can also occur through the upregulation of MET or HGF secretion signals, resulting in tumor transformation, in addition to gene amplification, mutation, or fusion." (PMID 39201787, 2024). "HGF is implicated in lymph angiogenesis and neo-angiogenesis, and serves as an inducer of tumor growth, invasion, and metastasis." (PMID 38816668, 2024). "Cytokines, HGF, C-X-C motif chemokine 12, and osteopontin, secreted from tumor-associated fibroblasts, promote the CD44v6 expression in the cancer-initiating cells, which promotes migration and metastasis of CRC cells." (PMID 36835416, 2023). "In this study, the combined use of capmatinib and entrectinib circumvented the resistance caused by HGF‐producing fibroblast MRC‐5 in a subcutaneous tumor model with KM12SM cells." (PMID 36416133, 2023).